APOE (apolipoprotein E)
Diseases named in the same sentence as APOE in open-access papers (continued):
Sharing a sentence is not in itself a finding about the gene and the disease.
atherosclerosis (continued). "In addition, the polyphenolic compound quercetin as well attenuates endothelial dysfunction and atherosclerosis in apoE deficient mice in a HO-1 dependent manner." (PMID 24847266, 2014). "This ensuing increase in oxidative burden could possibly underlie the difference in the extent of atherosclerosis we observed between the ApoE-null and DKO control animals." (PMID 24587793, 2014). "Data suggest that cola drinking at early life stages may predispose to atherosclerosis progression later in life in ApoE−/− mice." (PMID 24670925, 2014). "The ApoE-deficient mouse is a well-established model for the study of atherosclerosis." (PMID 23755169, 2014). "Previous results have demonstrated that atherosclerosis and inflammation with lipid peroxidation are accelerated in ApoE-deficient mice after an infection of periodontal bacteria and that these can be prevented by mucosal immunization with bacterial products or an anti-inflammatory agent." (PMID 24949459, 2014). "However, in a recent study, specific depletion of pDC in aortas and spleen of apoE-deficient mice was associated with significantly reduced atherosclerosis." (PMID 24904430, 2014). "In addition, TWEAK induces the expression of CCL19 and CCL21 in murine tubular cells, and both cytokines are also expressed in atherosclerotic plaques of ApoE-deficient mice, a model of hyperlipidemic-induced atherosclerosis." (PMID 24478772, 2014). "Genetic deficiency of iNOS reduces atherosclerosis in apolipoprotein E-knockout mice." (PMID 24662080, 2014). "Impaired efferocytosis, however, might also contribute to the development of the disease, as knock out mice deficient in efferocytosis are prone to develop atherosclerosis on LDL or ApoE null genetic backgrounds." (PMID 25136342, 2014). "As an adipocyte marker, aP2 modulates inflammatory responses and cholesterol ester accumulation, and deficiency in aP2 could protect against atherosclerosis and insulin resistance in the ApoE−/− mice." (PMID 23533476, 2013). "The aim of this work was to study the association of the Apolipoprotein E genotypes with coronary artery disease in the Iranian population and to evaluate the role of apolipoprotein E gene polymorphism as a predisposing factor for atherosclerosis patients." (PMID 23997914, 2013). "Recently, we reported that deletion of TRPV1 worsened atherosclerotic lesions in apolipoprotein E-deficient mice (ApoE−/−, a model of atherosclerosis-prone mice), so TRPV1 may have a role in atherogenesis." (PMID 23878415, 2013). "To investigate the role of ROS in atherosclerosis, we used ApoE-deficient mice, and compared the treatment effect of the antioxidant vitamin E with that of the angiotensin-converting enzyme (ACE) inhibitor, captopril, because angiotensin II is a major source of ROS in the vasculature." (PMID 23801967, 2013). "We therefore developed a Herp-deficient mouse model of atherosclerosis using apoE deficient mice, and studied whether Herp deficiency affects the development of atherosclerosis." (PMID 24204574, 2013). "To validate this hypothesis, in the current study we determined the impact of removal of the glucocorticoid function in APOE knockout mice on the outcome of two inflammation-associated pathologies, endotoxemia and atherosclerosis." (PMID 24265824, 2013). "The rising incidence of atherosclerosis and metabolic alterations warrants the study of long-term soft drink consumption’ effects on metabolism and atherosclerosis in genetic deficiency of apolipoprotein E which typically develops spontaneous atherosclerosis and metabolic alterations." (PMID 23547749, 2013).
atherosclerosis (continued). "Therefore, we explored the mechanisms that lead to long-term cardiac remodelling and investigated the interaction of radiation-induced damage to heart and cardiovascular systems with atherosclerosis, using wild-type and ApoE-deficient mice." (PMID 23451141, 2013). "The apolipoprotein E-deficient (apoE−/−) mouse, which spontaneously develops hypercholesterolemia and atherosclerotic lesions, has contributed to research concerning the role of oxidative stress in atherosclerosis." (PMID 23385237, 2013). "We could also demonstrate the novel finding that AdipoR2 deficiency has a protective effect on the progression of atherosclerosis in ApoE-/- mice." (PMID 24324556, 2013). "Furthermore, our recent study showed that Eb significantly attenuates pro-inflammatory and pro-atherosclerotic mediators as well as diabetes-associated atherosclerosis and diabetic nephropathy after 20 weeks of treatment in the diabetic ApoE/GPx1 dKO mice." (PMID 23874911, 2013). "Indeed, a protective effect against atherosclerosis was demonstrated in a mouse model of apolipoprotein-E deficiency upon overexpression of globular adiponectin." (PMID 23940810, 2013). "However, individuals homozygous for one dysfunctional variant of apoE, the apoE4 allele, are known to be at major genetic risk for developing atherosclerosis and sporadic Alzheimer's Disease (AD)." (PMID 23738020, 2013). "In order to determine whether a FGF receptor antagonist could affect atherosclerosis development, one month-old apoE-deficient mice were treated with SSR128129E (50mg/kg/d) for 3 and 5 months." (PMID 24224032, 2013). "Besides, the disruption of TNF-α gene diminishes the development of atherosclerosis in ApoE-deficient mice." (PMID 23895132, 2013). "Also, atherosclerosis is reduced in ApoE−/− mice deficient in TNFα and IFNγ potentiates atherosclerosis in these mice." (PMID 23560095, 2013). "Finally, apoE4 mouse model is considered useful for studying the role of human apoE polymorphism in atherosclerosis, lipid metabolism and Alzheimer's disease." (PMID 23738020, 2013). "Transgenic mice deficient in apolipoprotein E can serve as a genetic susceptibility model for cardiovascular disease because when fed a normal low fat diet they are susceptible to atherosclerosis, and on high fat diet the progression of the disease is known to be exacerbated." (PMID 23840332, 2013). "Also, immunization of ApoE−/− mice with PC linked to a carrier protein resulted in inhibition of atherosclerosis." (PMID 23874490, 2013). "More recent work suggests that other virulence factors of P. gingivalis may be equally important for the progression of atherosclerosis since the fimbriae-deficient strain W83 also promotes atherosclerosis in ApoE deficient mice." (PMID 23300720, 2012). "In addition, chronic activation of mPXR by PCN was reported to increase atherosclerosis in apolipoprotein E–deficient mice." (PMID 22214767, 2012). "Similarly, rosuvastatin and atorvastatin increases PPAR expression and attenuates atherosclerosis mice deficient in apolipoprotein E." (PMID 22315585, 2012). "In the present study, we crossed miR-33-deficient mice (miR-33−/−) with apoE-deficient mice (Apoe−/−) to examine the impact of miR-33 deletion on the progression of atherosclerosis and demonstrated that genetic loss of miR-33 raises circulating HDL-C and decreases atherosclerotic plaque size." (PMID 23316322, 2012). "Perhaps the most conclusive data were generated in the PON1-deficient mouse model and the human-PON1 transgenic mouse model, PON1 plus apolipoprotein E double-deficient mice showing increased lipoprotein oxidation and atherosclerosis than the apolipoprotein E-alone deficient mice." (PMID 22315585, 2012). "Furthermore, a number of population studies suggest that ApoE genotype predicts the risk of developing atherosclerosis and related diseases." (PMID 23193398, 2012).
atherosclerosis (continued). "However, despite the well established atheroprotective properties of macrophage-derived apoE, the consequences of its deficiency on atherosclerosis remain less well understood." (PMID 22606237, 2012). "Importantly, in our studies, ebselen was able to significantly improve diabetes-associated atherosclerosis and nephropathy in our ApoE/GPx1 dKO mice." (PMID 22013533, 2012). "For this reason, ApoE deficient mice are widely used to study atherosclerosis." (PMID 23193398, 2012). "As such, it is conceivable that lesion-associated apoE could promote atherosclerosis by mediating the retention of lipoproteins, thereby contributing to foam cell formation in the arterial wall." (PMID 22606237, 2012). "The similarities between atherosclerosis in humans and mice deficient either in apoE or the LDL receptor suggest that molecular mechanisms underlying regression in these mouse models could be relevant to the reduction in plaque burden in the human population." (PMID 22934038, 2012). "Interestingly, transgelin, an actin-binding protein abundant in smooth muscle cells is downregulated in atherosclerosis and a deficiency accelerates atherosclerosis in apoE–/– mice." (PMID 22276189, 2012). "The ApoE-deficient mouse model is a conventional model for investigating atherosclerosis." (PMID 22762010, 2012). "Thus, while deficiency of Gclm accelerates advanced atherosclerosis in ApoE null mice, overexpression of Gclc results in the opposite." (PMID 22833723, 2012). "In this paper, we describe the development and evaluation of new cathepsin activatable agents and their comparison to the new αvβ3 integrin targeted agent in the detection of atherosclerosis associated inflammation in apoE−/− mice using established FMT technology." (PMID 23119157, 2012). "Thus, this study was designed to examine the influence of macrophage-derived apoE expression levels on the susceptibility to diet-induced hyperlipidemia and atherosclerosis in mice that also expressed sub-physiological levels of apoE in all tissues." (PMID 22606237, 2012). "Additionally, we have shown that ebselen is protective against atherosclerosis in diabetic ApoE KO mice, which was associated with a decrease in oxidative stress markers and reduced expression of proatherogenic cellularity and mediators." (PMID 22013533, 2012). "Indeed, an infusion of Ang 1–7 is able to attenuate vascular dysfunction and atherosclerosis in genetically susceptible apolipoprotein E knockout (apoE KO) mice, possibly by increased activation of the Mas receptor and the type 2 angiotensin receptor (AT2)." (PMID 22536270, 2012). "AdPON3 in 26-week-old apolipoprotein E-deficient mice was also shown to protect against atherosclerosis, with mice showing significantly lower levels of serum lipid hydroperoxides and enhanced potential for cholesterol efflux from cholesterol-loaded macrophages." (PMID 22824324, 2012). "We show that central nervous system inflammatory pathology is associated with the development of atherosclerosis in high-fat diet–fed ApoE−/− mice and, through genetic deletion of IL-1R1 or neutralization of IL-1β, provide evidence that this is mediated by IL-1." (PMID 23130147, 2012). "In addition, EVO and polyphenol-enriched EVO have been demonstrated to moderately reduce atherosclerosis in ApoE-deficient mice." (PMID 21371300, 2011).
atherosclerosis (continued). "On the basis of these observations, we aim to investigate whether oral P gingivalis infection alters the vascular responsiveness in spontaneous atherosclerosis in apolipoprotein E-deficient (ApoE) mice compared with C57BL/6 (C57) wild-type mice." (PMID 21586133, 2011). "Specifically, adenovirus-mediated gene transfer of human lp-PLA2 prevented injury-induced neointima formation and reduced spontaneous atherosclerosis in ApoE-deficient mice as well as accumulation of oxidized lipoproteins, and inhibited inflammation and thrombosis in non-hyperlipidemic rabbits." (PMID 21909350, 2011). "Furthermore, Fabp4−/−Fabp5−/− mice intercrossed into an ApoE-deficient atherosclerosis model developed dramatically less atherosclerosis than that in FABP4-deficient or wild-type mice on the same background." (PMID 22121495, 2011). "Therefore, the deletion of the single apoE gene, which results in severe hypercholesterolemia, is sufficient to convert the mouse from a species that is highly resistant to atherosclerosis to one that is highly susceptible to the disease." (PMID 22082357, 2011). "Old age, atherosclerosis, stroke, hypertension, transient ischemic attacks, cardiac disease, the epsilon 4 allele of the apolipoprotein E (ApoE), elevated homocysteine levels, hyperlipidemia, metabolic syndrome, obesity and diabetes are risk factors for both vascular dementia and AD." (PMID 21439035, 2011). "Although previous studies implicated p38α signaling in atherosclerosis, our in vivo experiments suggest that p38α function in endothelial cells and macrophages does not play an important role in atherosclerotic plaque formation in ApoE deficient mice." (PMID 21695272, 2011). "The purpose of the current study on ApoE deficient mice is to assess the capacity of this stroke prevention innovation to influence atherosclerosis, a major underlying cause for ischemic strokes; human E-selectin is being translated as a potential clinical prevention strategy for secondary stroke." (PMID 21701687, 2011). "Finally, demonstrating its pathophysiological role, ER stress was shown to be strongly associated with accelerated atherosclerosis in hyperhomocysteinemic apoE-deficient mice, liver diseases as well as hyperglycemia-induced atherosclerosis." (PMID 21837278, 2011). "Moreover, apoE-/- mice that are genetically deficient in NADPH oxidase show retarded development of atherosclerosis in the aorta." (PMID 22082357, 2011). "Long-lived mice null for either pregnancy-associated plasma protein A (PAPP-A-KO), a metalloproteinase that degrades IGF-binding proteins, or p66shc are protected against high fat diet-induced atherosclerosis when maintained in an apolipoprotein E-deficient (ApoE) background." (PMID 21115536, 2011). "More convincingly, atherosclerosis prone male apolipoprotein E (apoE) deficient mice that also lack the AT1A receptor (double knock out) exhibit reduced atherosclerosis compared with wild type apoE KO mice." (PMID 21269478, 2011). "Deficiency of TLR3 accelerates the onset of atherosclerosis in ApoE-/- mice." (PMID 21526997, 2011). "This approach becomes even more appealing in light of new data demonstrating, that in isolated, genetically induced endothelial insulin resistance (mediated by endothelial-specific insulin receptor knock-out), dramatically enhanced development of atherosclerosis in an ApoE-deficient mice model." (PMID 21635764, 2011). "We have shown in previous studies that both fractionated irradiation and high single dose irradiation to the carotid arteries accelerate the development of atherosclerosis in apolipoprotein E-deficient (ApoE−/−) mice and predispose to the formation of an inflammatory, prothrombotic plaque phenotype." (PMID 20877628, 2010).
atherosclerosis (continued). "Based on this knowledge attempts have been made to develop immunomodulatory therapy for prevention of cardiovascular disease and pilot vaccines containing apolipoprotein B (apo B) antigens have been shown to significantly reduce atherosclerosis in apolipoprotein E deficient (Apoe-/-) mice." (PMID 21126329, 2010). "The objective of the present study was to verify whether inoculation of MP or in association with CP aggravates cholesterol-induced atherosclerosis in apoE KO mice." (PMID 19744321, 2009). "In various investigations ApoE was associated with a higher incidence of atherosclerosis." (PMID 19691831, 2009). "Recent population-based epidemiological studies suggested that vascular risk factors, such as vascular disease gene ApoE, hypertension, atherosclerosis, and heart failure, may impair cognitive functions and are related to the development of AD." (PMID 19649302, 2009). "Mice deficient in apolipoprotein E (apoE−/−) develop atherosclerosis." (PMID 18560564, 2008). "Also apoE deficient mice show high levels of cholesterol and develop spontaneous atherosclerosis while mice with partial or complete deficiency of high-mobility group A2 protein (Hmga2) are able to resist diet-induced obesity." (PMID 18959802, 2008). "To further evaluate this hypothesis we compared vascular TNF-α and TNF receptor expression in atherosclerosis-susceptible apoE-/-/LDL receptor-/- mice and control C57BL/6 mice." (PMID 23675033, 2007). "In support of this explanation, higher plasma concentrations of IL-10 have been detected in plasma of patients with stable, versus unstable coronary syndromes and, experimentally, IL-10 deficiency results in increased atherosclerosis in apolipoprotein E-deficient mice." (PMID 17328808, 2007). "In summary, this study shows that medial TNF-α and TNF receptor expression precedes lesion formation in the atherosclerosis-susceptible apoE-/-/LDL receptor-/- mouse, whereas the aortas of control C57BL/6 mice were essentially negative for TNF-α and TNF receptor immunoreactivity." (PMID 23675033, 2007). "Notably, NADPH oxidase deficiency has been shown to attenuate atherosclerosis in apoE(−/−) mice." (PMID 41031220, 2025). "Also, the deletion of the ApoE gene in mice increased their susceptibility to atherosclerosis." (PMID 40429697, 2025). "Preclinical studies in ApoE mice demonstrated that subcutaneous administration of the mAb induces anti-CS IgG1 antibodies, a Th2-associated subclass in mice, targeting lipoprotein retention without eliciting proinflammatory responses, a critical safety feature for atherosclerosis therapy." (PMID 40552286, 2025). "Thus, APOE allele-dependent cardiovascular effects, particularly through atherosclerosis, may significantly influence vascular pathways contributing to dementia." (PMID 40275327, 2025). "Similarly, ApoE−/− mice are widely used to study dyslipidemia-associated atherosclerosis in vivo." (PMID 40723828, 2025). "The APOE ε4 allele is associated with hypercholesterolemia, insulin resistance, chronic inflammation and atherosclerosis, which are also risk factors of AD, thus APOE ε4 carriership may diminish the effect of vegetable and fruit consumption on reducing dementia risk." (PMID 39890535, 2025). "While the study was conducted in animal models, which may not directly translate to humans, it serves as a cautionary reminder that dietary interventions like ADF should be approached with caution, especially for individuals at high risk of atherosclerosis, such as those carrying the ApoE-ε4 allele." (PMID 38736615, 2024). "In this study, we investigated the impact of ASGR1 deficiency (ASGR1−/−) on atherosclerosis by evaluating its effects on plaque formation, lipid metabolism, circulating immunoinflammatory response, and circulating N-glycome under the hypercholesterolemic condition in ApoE-deficient mice." (PMID 39616371, 2024). "Finally, USF1 deficiency relieved atherosclerosis in ApoE−/− mice through inhibiting EndMT." (PMID 38424494, 2024).